CXCL10 (C-X-C motif chemokine ligand 10)
Diseases named in the same sentence as CXCL10 in open-access papers (continued):
Sharing a sentence is not in itself a finding about the gene and the disease.
inflammatory bowel disease (32 papers, 2008 to 2025). A spectrum of small and large bowel inflammatory diseases of unknown etiology. "Previously, we reported colocalization of a locus regulating CXCL10 levels following Chlamydia trachomatis infection (rs2869462) and risk of inflammatory bowel disease." (PMID 34001247, 2021). "The role of CXCL10 has been contributed to be an important hallmark of in the of inflammatory bowel disease (IBD) pathophysiology." (PMID 18957084, 2008). "Further, we have shown previously that SNPs affecting expression of CXCL10 are also associated with risk of inflammatory bowel disease (IBD), with the direction of affect indicating that the rs2869462 risk allele for IBD (C allele) is associated with higher levels of CXCL109." (PMID 33106516, 2020). "Essentially, many comorbidities of rosacea, such as Alzheimer’s disease and inflammatory bowel disease have shown an association with chemokines CXCL9 and CXCL10 in the circulating serum." (PMID 36091020, 2022). "An inhibitor of CXCL10, eldelumab, has already been tested in clinical trials for inflammatory bowel disease." (PMID 31440239, 2019). "In inflammatory bowel disease, CXCL10 likely leads to intestinal barrier damage by virtue of its abundance and capability to stimulate myeloid-derived cells to produce tissue-damaging cytokines, such as IL-12, IL-23, and TNF-α." (PMID 29910805, 2018). "CXCL9, CXCL10 and CXCL11 can activate T cells by binding to C-X-C motif chemokine receptor (CXCR) 3 and have been implicated in a variety of autoimmune diseases, including thyroiditis, systemic sclerosis, and inflammatory bowel disease (IBD)." (PMID 35464480, 2022). "Although this study provides the first demonstration of the production of CXCL10 by enterocytes in the small intestine, similar results have been described in the colon, and recently, the upregulation of CXCL10 was observed in colonic enterocytes in inflammatory bowel diseases." (PMID 24586509, 2014). "Therefore, targeting CXCL10 may offer a novel treatment strategy for managing inflammatory bowel disease and regulating intraepithelial homeostasis." (PMID 40540498, 2025). "Interestingly, IFNγ-dependent gene modules were also induced in EGCs from patients with inflammatory bowel disease and chemokine interferon-γ-inducible protein (CXCL10) has been shown to be an “early immediate response” by EGC in response to intestinal injury-induced interferon λ signaling." (PMID 38147796, 2024). "The principal targets for anti-chemokine therapy in inflammatory bowel disease (IBD) have been the receptors CCR9 and CXCR3 and their respective ligands CCL25 and CXCL10." (PMID 30137309, 2018). "The inflammation and inflammatory bowel disease (IBD) disorders had many commonly modulated genes that were also found in the String analysis that were common with the disorders which included IL-8, ICAM1, RELB, NFκBIA, TNFAIP3, LIF, CXCL1, CXCL2, CXCL3, CXCL10, and TNF-α." (PMID 28099447, 2017). "CXCR3 and its ligands CXCL9, CXCL10, and CXCL11 are differentially elevated in many instances, such as with periodontal, autoimmune liver diseases, multiple sclerosis, bronchiolitis, skin or mucosal inflammation, cyclophosphamide (CYP)-induced cystitis, and inflammatory bowel disease (IBD)." (PMID 24278169, 2013).
Autoimmunity (31 papers, 2006 to 2025). The occurrence of an immune reaction against the organism's own cells or tissues. "Accordingly, the host must balance the expression of CXCL10, as too little signaling predisposes one to infectious disease, but too much signaling predisposes individuals to immune-mediated damage and autoimmunity." (PMID 33106516, 2020). "Interestingly, expression of Cxcl10 and Cxcl11, both of which have macrophage chemoattractant roles and are linked to autoimmunity and neuroinflammation, was most markedly upregulated in Nlrp12−/− retinas." (PMID 35313917, 2022). "Of the CXCR3 ligands, CXCL10 shows a strong association with autoimmunity." (PMID 24586509, 2014). "Previously, we developed a fusion protein that includes CXCL10 linked to the N-terminus of murine IgG1 Fc (CXCL10-Fc) for cancer therapy and CXCL11-Fc for therapy of autoimmunity." (PMID 39474427, 2024). "CXCL10 is one of the major triggers of early Th1/Th17-driven activation and polarization in allo- and autoimmunity, establishing and perpetuating a self-detrimental loop between local and systemic levels from the earliest stages of the response." (PMID 36077548, 2022). "This motivated us to develop a fusion protein that includes murine IgG1 Fc linked to CXCL10 (CXCL10-Ig or CXCL10-Fc) for cancer therapy, and CXCL11 fused to the same construct for therapy of autoimmunity (CXCL11-Ig or CXCL11-Fc)." (PMID 34944943, 2021). "As for autoimmunity, the role of CXCL10 and CXCL11 has been largely studied by several laboratories including ours, whereas the role of CXCL9 is still elusive." (PMID 32547545, 2020). "Collectively, this suggests that CXCL10 promotes the polarization of Th1 cells, thus its targeted neutralization restrains autoimmunity." (PMID 32547545, 2020). "In fact, different studies have revealed that CXCL10 plays a unique and important role in imprinting a pattern for the subsequent development of autoimmunity." (PMID 24586509, 2014). "Increased levels of circulating CXCL10 have been detected in inflammatory processes and autoimmunity." (PMID 24586509, 2014). "Our AUCs for serum CXCL9, CXCL10 and CXCL11 in the differential diagnosis of CVD–ILD from IPAF and IPF suggest that these serum chemokines may be diagnostic biomarkers of ILD with autoimmunity." (PMID 33137121, 2020). "We then assessed the associations of CXCL9, CXCL10, and CXCL11, that were different between groups, with clinical characteristics, diagnosis, and treatment responsiveness to identify biomarkers of inflammation in ILD with background autoimmunity." (PMID 33137121, 2020). "The controversy of the role of CXCL10 in neuroinflammation, particularly when comparing systemic administration of anti CXCL10 neutralizing antibodies vs. using CXCL10 KO mice should be further addressed, particularly if one would like to consider anti CXCL10 based therapy for autoimmunity." (PMID 32547545, 2020). "Thus, evasins that preferentially bind CXCL10 may be useful tools to modulate T-cell–mediated autoimmunity." (PMID 31167786, 2019). "This study demonstrated that in patients with CVD–ILD and IPAF with background autoimmunity, serum and BALF levels of CXCL9, CXCL10, and CXCL11 were significantly higher than those in patients with IPF." (PMID 33137121, 2020). "Serum CXCL9, CXCL10, and CXCL11 are potential biomarkers for autoimmune inflammation and predictors of the immunosuppressive therapy responses in ILD with background autoimmunity." (PMID 33137121, 2020). "CXCL10 and CXCL11 have been suggested to have opposite activities with CXCL10 promoting and CXCL11 suppressing T-cell–mediated autoimmunity." (PMID 31167786, 2019). "The basic rational is that the stabilized form of chemokines that induce Tr1-like cells, among them CXCL12 and CXCL11, could be used for therapy of autoimmunity and GVHD, whereas stabilized CXCL10 would be used for cancer therapy." (PMID 26648938, 2015).
Autoimmunity (continued). "Our results suggest that high serum CXCL9, CXCL10, and CXCL11 levels may reflect reversible inflammation and that these chemokines are predictive biomarkers of the response to immunosuppressive therapy in ILD with background autoimmunity." (PMID 33137121, 2020). "Serum CXCL9, CXCL10, and CXCL11 may reflect autoimmune inflammation of ILD and work as biomarkers to predict the response to immunosuppressive therapy in the management of ILD with background autoimmunity." (PMID 33137121, 2020). "Unlike the pro-inflammatory CXCL10, CXCL11 promotes the development of IL-10–producing regulatory T cells, which help control autoimmunity." (PMID 40969764, 2025).
encephalitis (31 papers, 2012 to 2025). An acute inflammatory process affecting the brain parenchyma. "CXCL10 expression was observed in several organs, especially the brain of NiV-infected golden hamster; thus, CXCL10 was suggested to play a role in the development of NiV-associated encephalitis." (PMID 35744680, 2022). "CXCL9 and CXCL10 are hallmarks of many viral CNS infections including encephalitis caused by HSV-1 and meningitis caused by HSV-2." (PMID 30777092, 2019). "Patients with meningitis, encephalitis or meningoencephalitis caused by TBEV showed increased concentrations of CXCL10 and CXCL11 in the CSF and elevated CXCL10 levels in blood, indicating their potential role as biomarkers of inflammatory processes in the CNS." (PMID 40918112, 2025). "As equilibrium in cytokine production is essential in the generation of the adequate immune response, CXCL10 overexpression may be crucial for the development of NiV-associated encephalitis and could be a target for therapeutic approaches." (PMID 22393386, 2012). "Some of these molecules (CXCL13 and CXCL10) may represent potential therapeutic targets in view of their association with severity of encephalopathy at admission and worse disability at follow up in all encephalitis cases." (PMID 27575749, 2016). "In a mouse model of WNV encephalitis, neurons were identified as an additional source of CXCL10, inducing recruitment of CD8+ T cells." (PMID 40918112, 2025). "IP10 or CXCL10 is a chemokine induced by TNFα and IFNγ and has been implicated in various neuroinflammatory conditions, including viral encephalitis, bacterial meningitis, and CM, where it serves as a potential biomarker for mortality prediction." (PMID 39273566, 2024). "Meta-analysis of 204 encephalitis patients and 73 controls showed that the CSF levels of the CXCL10 are higher in the encephalitis group than in the control group (SMD, 0.86; 95% CI, 0.16–1.56; P = 0.02)." (PMID 36048783, 2022). "This meta-analysis serves as evidence that encephalitis patients had greater CSF concentrations of IL-6, IL-8, IL-10, CXCL10, and TNF-α when compared to controls." (PMID 36048783, 2022). "According to the analyses, patients with encephalitis had higher CSF amounts of IL-6, IL-8, IL-10, CXCL10, and TNF-α than healthy controls." (PMID 36048783, 2022). "The subgroup analysis in the infectious encephalitis, similar to the overall meta-analysis, demonstrated a higher CSF concentration of the CXCL10 in the encephalitis patients compared to the controls (SMD, 1.16; 95% CI, 0.22–2.10; P = 0.02)." (PMID 36048783, 2022). "Higher expression of CXCL10 leads to apoptosis in viral encephalitis through triggering a caspase cascade." (PMID 35604176, 2022). "Th1 and B cell (CXCL13 and CXCL10) molecules clustered together in patients with severe encephalopathy at admission and worse disability at follow up in all encephalitis." (PMID 27575749, 2016). "In descending order, CSF TNF-α, IL-10, IFN-α, IL-6, CXCL13 and CXCL10 had the best sensitivity (>79.1%) when all encephalitis patients were included." (PMID 27575749, 2016). "In our cohort of encephalitis, the Th1 (CXCL10 & TNF-α), T reg (IL-10), B cell (CXCL13) related cytokine/chemokines, and cytokines with broad spectrum of activities including IL-6 and IFN-α, were elevated in more than 75% of the cases." (PMID 27575749, 2016). "Although disease progression was faster in SARS-CoV-2 infected mice, infection with both viruses resulted in neuronal infection and encephalitis with increased expression of Interferon-stimulated Irf7, Bst2, Ifi294, as well as CxCL10, CCL5, CLC2, and LILRB4, and both models were uniformly lethal." (PMID 35967447, 2022). "In addition, the serum/plasma levels of the TNF-α were increased in encephalitis patients, but serum/plasma concentration of the IL-6, IL-10, CXCL10, and CXCL13 remained unchanged." (PMID 36048783, 2022). "The serum levels of CXCL10 were elevated in CASPR2 encephalitis." (PMID 33396564, 2020).
encephalitis (continued). "However, a specific focus on samples from patients with encephalitis revealed increased CXCL10 levels compared with patients with demyelinating disorders or controls." (PMID 31356620, 2019). "Infiltrates of lymphocytes and loss of neurons were identified in the histological examinations of the cases of VA1 encephalitis (9, –, 11), and CXCL10 could be an important mediator of this observed inflammatory response to infection." (PMID 31289185, 2019). "Interestingly, CXCL10 levels exceeded the threshold (317 pg/mL) in 82% (9/11) of patients with NB and in 66% (18/27) of patients with encephalitis (ADEM, NMDARE, RE, or ENC) but only in 24% (5/17) of patients with MS and in 4% (1/25) of patients with CIS." (PMID 31356620, 2019). "CCL19, CXCL8, CXCL9, and CXCL10 were significantly increased compared to CSF from control patients and compared to levels in serum in patients with encephalitis, meningitis, and Ramsay Hunt syndrome whereas CXCL11 was only increased in CSF in VZV meningitis patients." (PMID 30777092, 2019). "Indeed, during viral encephalitis neurons secrete CXCL10 to recruit anti-viral effector CD8+ T cells, demonstrating that neuronal cells specifically shape immune responses against invading pathogens." (PMID 30254622, 2018). "Given their association with worse outcome, certain key chemokines (CXCL13, CXCL10) could represent potential therapeutic targets in encephalitis." (PMID 27575749, 2016). "This study sheds new light on NiV pathogenesis, indicating the role of CXCL10 during the course of infection and suggests that this chemokine may serve as a potential new marker for lethal NiV encephalitis." (PMID 22393386, 2012). "Alteration of CCL-4, CCL-17, CCL-20, CXCL10, CXCL-13, and TNF-α, IFN-γ, IL-2, IL-4, IL-5, IL-6, IL-9, IL-10, and IL-22 have been reported in the CSF or serum/plasma of patients with encephalitis." (PMID 40717731, 2025). "The alteration in the concentration of the different chemokines, such as CXCL10, CXCL-13, CCL-4, CCL-17, CCL-20, and cytokines, including IL-2, IL-4, IL-6, IL-9, IL-10, and IFN-γ have been observed in encephalitis patients." (PMID 36048783, 2022). "This meta-analysis provides evidence for higher CSF concentrations of IL-6, IL-8, IL-10, CXCL10, and TNF-α in encephalitis patients compared to controls." (PMID 36048783, 2022). "According to previous studies on cerebrospinal fluid (CSF) chemokines in EV71 patients with encephalitis or meningoencephalitis (ME), CSF IL-6, IL8, CCL5 and CXCL10 concentrations were significantly higher compared to patients with febrile convulsion (FC)." (PMID 31575039, 2019). "The potential role of monoclonal antibodies against CXCL10, CXCL13 as therapeutic targets in encephalitis needs further investigation." (PMID 27575749, 2016). "Of 3 cases studied with encephalitis relapses, IFN-α was elevated all cases where as CXCL10 and CXCL13 were elevated only in two cases." (PMID 27575749, 2016). "We observed that TNF-α, IL-10, IFN-α, IL-6, CXCL10 and CXCL13 demonstrated >79.1% sensitivity in patients with encephalitis using control 95th centile as cut off (specificity 95%)." (PMID 27575749, 2016). "IL-2, CXCL10, CCL3, IL-10, CCL22, and IL-6 may represent new biomarkers in patients with anti-NMDAR encephalitis." (PMID 33408682, 2020). "Elevated intrathecal CXCL10 production has been noted in patients with infectious and noninfectious encephalitis, as well as in patients with MS." (PMID 31356620, 2019). "We demonstrate that CNS complications caused by VZV virus are associated with highly elevated CSF levels of the chemokines CCL19, CXCL8, CXCL9, CXCL10, and the matrix metalloproteinase MMP-2 in patients with different CNS manifestations such as encephalitis, meningitis, and Ramsay Hunt syndrome." (PMID 30777092, 2019). "Based on accumulating evidence, CSF CXCL10 levels are elevated in patients with encephalitis of either an infectious or noninfectious etiology." (PMID 31356620, 2019).
encephalitis (continued). "We have demonstrated the CSF cytokines CXCL10/IP-10 and IL-21 are potential differentiators of AE from viral encephalitis, particularly when there is no CNS specific autoantibody detected." (PMID 32116981, 2019).
gastric cancer (31 papers, 2011 to 2025). A primary or metastatic malignant neoplasm involving the stomach. "Chemokine (C-X-C motif) ligand 10 (CXCL10) has been implicated in the promotion of gastric cancer invasion and carcinogenesis." (PMID 37952025, 2023). "RHOA mutated gastric cancer cells reduced the secretion of CXCL10 and CXCL11, and stimulated the synthesis of fatty acids through the PI3K-AKT-mTOR pathway, which in turn enhances the inhibition of regulatory T cells (Tregs) within the TIME, thereby inducing immunosuppression." (PMID 40149008, 2025). "The tumor-immune microenvironment in gastric cancer, influenced by m6A modifications, is intricately modulated under hypoxic conditions, with CXCL10 emerging as key mediator in tumor-immune interactions." (PMID 39824841, 2025). "Plasma levels of IL-8, CXCL9, and CXCL10 were greatly increased in patients with gastric cancer, while being decreased after surgery." (PMID 36612163, 2022). "A constructed miRNA-mRNA network showed that CXCL5, CXCL9, and CXCL10 are target genes of miR-588, and high expression of miR-588, CXCL5, CXCL9, and CXCL10 is associated with the prolonged survival in gastric cancer patients." (PMID 34283058, 2021). "In a cohort of gastric cancer (GC) patients, the expression of CXCL10 has a positive correlation with patient prognosis and induces T lymphocyte migration and infiltration into the GC 3D cell culture model." (PMID 33324568, 2020). "Interferon-gamma-inducible protein 10 (IP-10/CXCL10) expression was increased in gastric carcinoma tissues displaying reduced PML levels." (PMID 22022583, 2011). "Additionally, 2 Gy of IR increased T lymphocyte recruitment by increasing CXCL9 and CXCL10 levels in AGS-EBV human gastric cancer cells." (PMID 37048082, 2023). "As shown in previous studies, the VEGF-PIK3/AKT pathway activated by CCL5 promoted tumor metastasis by stimulating angiogenesis and ECM remodeling, and the robust expression of CXCL10 also enhanced gastric cancer invasion and metastasis by binding the receptor CXCR3A." (PMID 35692828, 2022). "However, the involvement of autophagy in regulating CXCL10 expression in gastric cancer (GC) cells and T lymphocyte migration remains unclear." (PMID 32582551, 2020). "In the comparison of metabolite interference group and M1 group marker proteins in gastric cancer cells, there were significant differences in IL-6, CXCL9, CXCL10 and CXCL11." (PMID 39991579, 2025). "CXCL9, CXCL10 and CXCL11 have especially been considered as IFN-γ response cytokines and have been reported to modulate the expression of PDL-1 in gastric cancer cells." (PMID 36766722, 2023). "miR-135a-5p targets CASP1, CXCL10, and transmembrane protein 140 (TMEM140), which are known to be involved in the proliferation of gastric cancer cells and the expression of IFN-α." (PMID 37952025, 2023). "The invasion and migration of gastric cancer cells can be promoted by MMP-2 and MMP-9, which are upregulated by the CXCL10/CXCR3 axis." (PMID 34367971, 2021). "Conversely, TRIM6 depletion in mouse (MTC) and human (MKN28) gastric cancer cells resulted in a significant increase in the mRNA levels of IFNB1 and its downstream genes CXCL10 and ISG15 (or Ccl5) under HT-DNA treatment, and these effects were abolished by simultaneous cGAS knockout." (PMID 40817248, 2025). "In addition, MK1775 treatment significantly increased the expression of proinflammatory cytokines such as CCL20, CXCL10, and IFN-β in MUS81 knockdown cells, but increased expression modestly in parental gastric cancer cells." (PMID 34625086, 2021). "Chemokine gene expression signatures including CCL5, CXCL9, CXCL10, and CXCL11 were reported that could accurately predict anti-PD-1 immunotherapy response for patients with head and neck squamous cell carcinoma and gastric cancer." (PMID 32316408, 2020).